GRK2 (G protein-coupled receptor kinase 2)
Diseases named in the same sentence as GRK2 in open-access papers (continued):
Sharing a sentence is not in itself a finding about the gene and the disease.
kidney diseases (2 papers, 2021 to 2024). "Further studies are encouraged to bridge the gaps in our understandings the roles of GRK2 in renal disorders." (PMID 39438268, 2024). "Although advances have been made toward developing inhibitors that are selective for GRK2, safe and effective GRK2 inhibitors for kidney disease still need to be studied by silico investigation and chemical and biological experiments." (PMID 39438268, 2024). "Above all, there are great potentials for researchers to develop selective GRK2 inhibitors to treat renal diseases." (PMID 39438268, 2024). "Drug selectivity is an important and challenging difficulty in renal disease treatment with GRK2 inhibition." (PMID 39438268, 2024). "For the first time, our review summarized the role of GRK2 in renal diseases and provides many feasible entry points for GRK2 research in the field of kidney disease in the future." (PMID 39438268, 2024). "Though partial GRK2 inhibition plays a positive role in the therapy of many renal diseases, total inhibition of GRK2 can have deleterious outcomes on kidney function and development." (PMID 39438268, 2024). "Abnormal GRK2 expression contribute to the development of renal diseases, making them promising molecular targets for treating renal diseases." (PMID 39438268, 2024). "As GRK2 is ubiquitously distributed in the human kidney, its therapeutic potential in a variety of renal diseases cannot be ignored either." (PMID 39438268, 2024). "Links between GRK2 and histopathological alterations in the kidney suggest potential therapeutic strategies to prevent kidney disease progression and portray GRK2 as a promising therapeutic target." (PMID 39438268, 2024). "GRK2 knockout rat model has been used to investigate the effects of GRK2 in kidney diseases, continues studies investigate that severer kidney-specific damage was occurred in GRK2 knockdown mice." (PMID 35111168, 2021). "Selective GRK2 inhibition might be an innovative therapeutic strategy to treat renal diseases in which GRK2 overexpression leads to dysregulated signalling pathways." (PMID 39438268, 2024). "However, there is still a long way to go for the large‐scale application of GRK2 inhibition in the field of renal diseases." (PMID 39438268, 2024). "The therapeutic potential of GRK2 in DN had attracted much attention among the renal diseases." (PMID 39438268, 2024). "In order to facilitate the research of GRK2 in the field of kidney diseases and promote its clinical application in the treatment of kidney diseases, this review will systematically summarize the current state of research on the roles of GRK2 in renal diseases." (PMID 39438268, 2024). "In addition, the potential of GRK2 in the treatment of kidney disease is also beginning to show." (PMID 39438268, 2024). "The number of studies on GRK2 in the field of kidney diseases is not as large as that in the field of cardiovascular diseases, but it has been gradually improved in recent years." (PMID 39438268, 2024).
peripheral neuropathy (2 papers, 2022 to 2025). A disorder affecting the peripheral nervous system. "Our previous study demonstrated that neuronal G protein-coupled receptor kinase (GRK2) upregulation alleviated chemotherapy-induced peripheral neuropathy (CIPN) in mice, which was characterized by numbness and pain in distal hind limbs." (PMID 41276799, 2025). "Consistent to present work, our recent study also demonstrated the contribution of the neuronal GRK2 in the preventive effect of EA on the development of cisplatin-induced peripheral neuropathy." (PMID 35115050, 2022).
immunodeficiency (1 paper, 2025). Failure of the immune system to protect the body adequately from infection, due to the absence or insufficiency of some component process or substance. "In a mouse model of immune hepatitis, coexpression of GRK2 with PI3K regulates T lymphocyte lipid metabolism, reduces Treg activity, and leads to immunodeficiency in immune hepatitis." (PMID 40224487, 2025).
GRK2 also shares sentences with these, for which no sentence is quoted: multiple sclerosis (7 papers); acute myocardial infarction (3); autoimmune hepatitis (3); Hyperinsulinemia (3); Anxiety (2); dementia (2); Hepatitis (2); hypertrophy (2); infarction (2); ischemic disease (2); melanoma (2); neurodegenerative disease (2); prostate tumors (2); systolic heart failure (2); viral infection (2); acute kidney injury (1); alcohol use disorders (1); allergies (1); amyloid (1); autoimmune disorders (1); bacterial infection (1); bladder cancer (1); Cerebral ischemia (1); cerebrovascular disease (1); chondrosarcoma (1); chronic lymphocytic leukemia (1); chronic pancreatitis (1); colon cancer (1); congenital heart disease (1); E. coli (1).
A further 36 diseases each share a sentence with GRK2 in 1 paper.